ALCAM (activated leukocyte cell adhesion molecule)
Diseases named in the same sentence as ALCAM in open-access papers (continued):
Sharing a sentence is not in itself a finding about the gene and the disease.
cancer (continued). "By comparing the differential capacity of immobilized ALCAM+ and ALCAM− EVs to support the adhesion of wild-type (ALCAM+) and ALCAM-KO (ALCAM−) SKOV-3 and Colo-320 cells, we established that ALCAM/CD166 is involved in EV interactions with recipient cancer cells." (PMID 35628559, 2022). "Similarly, activation of SHH (sonic hedgehog) has been shown to increase the protein half-life of ALCAM in oral SCC cells, arguing a protein-level regulation of ALCAM in cancer." (PMID 34680335, 2021). "ALCAM was expressed in 69% of Wnt5a-positive but only 27% of Wnt5a-negative cancers (κ = 0.444; P < 0.001)." (PMID 29765514, 2018). "CD133, a glycosylated five-transmembrane protein, and CD166, an activated leukocyte cell-adhesion molecule, represent cancer stem cell markers with a negative prognostic role in many solid tumors." (PMID 28709442, 2017). "Moreover, ALCAM-specific CAR-T cells can efficiently lyse CRC cells and show powerful cytotoxicity against CRC stem cells, demonstrating a feasible approach for reconstructing CAR-T cells with S100A8/A9 and its receptors for cancer therapy." (PMID 37701037, 2023). "Many of these other potential enhancer-hijacking targets do not have well-established roles in cancer pathogenesis, however, we did notice a number of genes involved in cell adhesion (ALCAM, NCAM2, CADM2, and CDH9) and 2 SLIT and NTRK like family members (SLITRK1, SLITRK6)." (PMID 35538064, 2022). "To study the involvement of ALCAM/CD166 in the interactions and ensuing uptake of EVs produced by OvC (SKOV-3) and CRC (Colo-320) cells, we first suppressed the expression of this molecule in both cancer cell lines by using the CRISPR/Cas9 gene knock out technique." (PMID 35628559, 2022). "The known relevance of CD6-CD166/ALCAM interaction in cell-to-cell adhesive contacts established between T cells and other immune (B cells, macrophages, dendritic cells) and non-immune (endothelial, epithelial) cells warrants future studies of CD6 variation in cancer." (PMID 34070159, 2021). "In 8 cases (7.7 %) no ALCAM immunoreactivity was detected in cancer cells." (PMID 26134500, 2015). "However, there is no consistent correlation between ALCAM expression level and patient survival across all cancers." (PMID 23024593, 2012). "Extracellular CSC markers that have been implicated in PCa but are not always specific to this cancer type per se include CD117/c-kit, CD133, CD44, α2β1 integrin, α6 integrin, CXCR4, E-cadherin, EpCAM, Cytokeratin 5, PSA, ABCG2, Trop2, AR variant 7, and CD166/ALCAM." (PMID 33841508, 2021).
infection (9 papers, 2012 to 2025). The state of being infected such as from the introduction of a foreign agent such as serum, vaccine, antigenic substance or organism. "Through intercellular communication analysis, inflammatory signaling pathways, such as the CCL, TNF, CXCL, complex, and ALCAM pathways, were found to increase and enhance cellular communication after infection." (PMID 39590301, 2024). "We thus also analyzed ALCAM expression on PD-1+ effector T cells at the chronic stage of infection (day 30) and found a significantly higher proportion of ALCAM+ cells within PD-1+ effector T cells compared to PD-1- controls or naïve T cells." (PMID 33375121, 2020). "We examined the effect of wild-type or early-region gene-mutated adenovirus [E1B-55k-(dl1520), E4orf3-(pm4150), E4orf6-(pm4154), E4orf3-/E4orf6-(pm4155)] infection on ALCAM, EPHA2 and PTPRF." (PMID 28631589, 2017). "ALCAM protein was degraded by wild-type adenovirus and the analysis of infection with single or double mutants revealed that there appear to be two or more mechanisms promoting degradation." (PMID 28631589, 2017). "We could indeed observe a steady increase of ALCAM expression in both T cell populations that was maintained throughout the course of infection." (PMID 33375121, 2020). "Potentially, the clearance of ALCAM during infection might inhibit ALCAM-dependent immune responses and promote adenovirus propagation." (PMID 28631589, 2017). "WT B6 mice were infected with LCMV clone 13, and ALCAM expression on CD4+ and CD8+ T cells was analyzed during the acute (day 8) and chronic (day 30) phase of the infection and compared to naïve mice (day 0)." (PMID 33375121, 2020). "The increased expression of JAM-A and ALCAM on the monocytes in HIV infection is induced directly by the infection of monocytes and is not secondary to viral proteins’ exposure or by cytokines associated with HIV infection." (PMID 39685490, 2024). "To assess whether infection changed the expression of junctional proteins essential to CD14+ CD16+ monocyte transmigration, we examined surface JAM-A and ALCAM on HIV+ and HIVexp CD14+ CD16+ monocytes." (PMID 29066542, 2017).
renal disease (6 papers, 2020 to 2022). "Of both, higher levels of VCAM-1 in urine could be indicative of a long-term renal function loss, while ALCAM could be used as a potential biomarker of kidney disease." (PMID 34281193, 2021). "Together, these data suggest that the CD6/ALCAM pathway plays a role in both renal disease as well as systemic disease in SLE." (PMID 34981775, 2022). "Correlation analysis revealed that urinary ALCAM levels correlated significantly with both global disease activity and renal disease activity." (PMID 32460901, 2020). "Compared to conventional markers, such as 24-h urine protein, AUC for ALCAM exceeded AUC for proteinuria in distinguishing class III/IV from V. Conventional markers have been examined in various studies as biomarkers of renal disease activity." (PMID 32460901, 2020). "Correlation analysis revealed a positive correlation between urinary ALCAM and general disease activity—SLEDAI score (r = 0.487, p < 0.001), as well as renal disease activity—rSLEDAI (r = 0.552, p < 0.001) and SLICC RAS (r = 0.584, p < 0.001)." (PMID 32460901, 2020). "We found a positive correlation between urinary ALCAM with both global disease activity (vs SLEDAI, r = 0.487, p < 0.001) and renal disease activity (vs rSLEDAI, r = 0.552 p < 0.001; vs SLICC RAS, r = 0.584, p < 0.001)." (PMID 32460901, 2020). "In addition to being significantly increased in active LN patients, urine ALCAM correlated significantly with total and renal SLEDAI score and exhibited excellent ability to distinguish cSLE patients with active renal disease." (PMID 35720325, 2022). "To further assess the relationship between urinary ALCAM and disease activity, we performed a correlation analysis between urinary ALCAM levels and disease activity index including SLEDAI for global disease activity and rSLEDAI and SLICC RAS for renal disease activity." (PMID 32460901, 2020). "More interestingly, urinary ALCAM also correlated with renal pathology activity index but not the chronicity index, which is concordant with the observed correlation with clinical renal disease activity." (PMID 32460901, 2020).
central nervous system tumors (1 paper, 2020). "Few studies have investigated the expression of ALCAM in MB; among them, one study assessed ALCAM levels in various primary central nervous system tumors, including MB." (PMID 33270750, 2020).
ALCAM also shares sentences with these, for which no sentence is quoted: osteoarthritis (6 papers); adenocarcinoma (5); head and neck squamous cell carcinoma (4); Arthritis (3); atherosclerosis (3); colorectal tumours (3); head and neck cancer (3); multiple myeloma (3); Behçet's disease (2); cognitive deficits (2); colorectal adenocarcinoma (2); coronary artery disease (2); esophageal squamous cell carcinoma (2); food allergies (2); Insulin resistance (2); leukemia (2); metastasis (2); renal carcinoma (2); adrenocortical cancer (1); Allergy (1); ameloblastoma (1); anaplastic ependymoma (1); ANCA-associated vasculitis (1); astrocytoma (1); autism spectrum disorder (1); bladder tumors (1); bone disorder (1); bone metastasis (1); brain cancer (1); chronic obstructive pulmonary disease (1).
A further 56 diseases each share a sentence with ALCAM in 1 paper.